IDH1 (isocitrate dehydrogenase (NADP(+)) 1)
Diseases named in the same sentence as IDH1 in open-access papers (continued):
Sharing a sentence is not in itself a finding about the gene and the disease.
glioma (continued). "Further in-depth studies on the effect of IDH1 mutation in glioma on gene expression profiling might help to develop new therapeutic strategies for the lethal disease." (PMID 31443404, 2019). "IDH1/R132 and IDH2/R172 are commonly found in gliomas, cholangiocarcinomas, and chondrosarcomas, with a higher frequency of IDH1/R132 mutation occurring in these cancers (58%–90%, 40%–50%, and 50%–60% respectively) compared to IDH2/R172 (3%–5%, 5%–10%, and 10%)." (PMID 31817761, 2019). "Similarly, the ITSS grades of IDH1-mutated gliomas were much lower than those of Wild-type gliomas (p < 0.001), and the ITSS grades of MGMT-methylated gliomas were much lower than those of MGMT-unmethylated gliomas (p < 0.001)." (PMID 31745161, 2019). "IDH1/2 is mutated in ~70–80% of lower-grade gliomas and the majority of secondary glioblastomas." (PMID 30857299, 2019). "All reasons for which glioma patients with IDH1 mutations show better therapeutic responses and longer survival remain unclear." (PMID 30857299, 2019). "This indicates that IDH1 mutation causes metabolic reprogramming in cells and these metabolic changes may contribute glioma pathogenesis." (PMID 31278288, 2019). "IDH1/2 mutated glioma has been associated with a germline risk variant, the rs55705857 G allele." (PMID 30823903, 2019). "Our detailed data analysis of biochemicals could clearly separate glioma samples with IDH1 mutation from normal IDH1 glioma samples." (PMID 31278288, 2019). "Of all gliomas, IDH1 revealed a higher mutation rate than IDH2." (PMID 31450822, 2019). "The mutated IDH1-R132H vaccines were developed and proven to be effective in launching antitumor immunity in preclinical models, which led to initiation of a clinical trial in glioma patients." (PMID 30857299, 2019). "However, none of these studies considered isocitrate dehydrogenase 1 (IDH1) mutation status for survival analysis, although IDH1-mutant (IDH1-mut) gliomas comprise a molecularly distinct GBM subgroup with favorable patient outcomes." (PMID 30669568, 2019). "The presentation of mixed results in glioma models is likely due to the fact that certain tumorigenic processes are uncoupled from the IDH1 mutation, and further studies into combination treatment (discussed in a later section) may be warranted." (PMID 31165048, 2019). "Therefore, IGFBP2, EGFR_pY1068, HER2_pY1248, and EGFR_pY1173 are affected in the same way by IDH1 mutations in low-grade glioma and glioblastoma, and we report a cross-cancer effect for those groups." (PMID 30442178, 2018). "Interestingly, the expression levels of PRMT1, PRMT2, PRMT4, and PRMT6 in low-grade gliomas are significantly higher in IDH1/2 wild-type (WT) subgroups than the subgroups with the IDH1/2 mutations." (PMID 30382083, 2018). "Among gene targets of probes demonstrating a positive correlation between 5hmC and increased gene expression in IDH1 mt tumors (Group 1) were several genes implicated in glioma pathogenesis, including leucine-rich repeat containing G protein-coupled receptor 5 (LGR5)." (PMID 29428975, 2018). "Mutation of IDH-1 in glioma induces the HIF-1 pathway by reducing α-KG production." (PMID 30367042, 2018). "Furthermore, these authors showed that IDH1-WT primary glioblastomas, at variance with wild IDH1-mutated low-grade gliomas, have a low risk of temozolomide-induced hypermutation." (PMID 30279357, 2018). "Furthermore, deletion or amplification of either mutant or wild-type IDH1 allele decreases D2-HG in glioma recurrence." (PMID 30416682, 2018). "Therefore, we also analysed glioma VAMCs, constituting the cellular source of EMT transcription factors in our cohort, for the most frequent and specific glioma-associated genetic aberrations namely IDH1 mutation, 1p/19q LOH as well as EGFR amplification." (PMID 29844871, 2018).
glioma (continued). "Although IDH mutation is retained upon glioma recurrence, mutant IDH1 may convert from driver to passenger, and, in some patients, neither mutant IDH1 nor the oncometabolite 2HG are strictly required for clonal expansion at recurrence." (PMID 29642018, 2018). "In this classification, IDH1 mutations, the codeletion status of chromosome arms 1p and 19q, and the histone 3 mutational status can be used to distinguish between biologically distinct glioma." (PMID 30388142, 2018). "Mutations in IDH1/IDH2 are commonly considered to be glioma initiating." (PMID 29616301, 2018). "There is evidence to support the notion that IDH1 mutations may be associated with glioma susceptibility." (PMID 29643764, 2018). "Moreover, several studies indicated that the R132H mutation of IDH1 correlates with a favorable prognosis for patients with glioma and gastrointestinal cancer." (PMID 30153799, 2018). "IDH1 somatic mutation has been linked to a glioma-CpG island methylator phenotype (G-CIMP)." (PMID 29168083, 2018). "Nevertheless, our results suggest that epigenetic alterations in gliomas caused by the IDH1 mutation could be one of the mechanisms of action underlying the distinct immunological features between IDH1-mutant and wildtype tumors." (PMID 29643764, 2018). "Somatic IDH1 mutations were primarily identified in low-grade gliomas." (PMID 30305430, 2018). "Mutations of IDH1 offer the opportunity to develop an effective treatment against gliomas." (PMID 29662077, 2018). "IDH1 mutations are oncogenic mutations found in 74% of low-grade gliomas and 9% of GBM." (PMID 30723695, 2018). "Diffuse gliomas in adults are now separated into three comprehensive tumor groups with distinctive prognoses, based on the status of isocitrate dehydrogenase genes 1 and 2 (IDH1/2) mutations and 1p/19q-codeletion." (PMID 29693015, 2018). "Previous research has shown that IDH1 mutations result in the production of the oncometabolite 2HG, and the accumulation of this product in vivo contributes to the formation and malignant progression of gliomas." (PMID 29643764, 2018). "Thus, it is believed that D-2HG mediated inhibition of α-KG dependent dioxygenases is one major reason through which IDH1/2 mutations contributing to the pathogenesis of either glioma or leukemia." (PMID 29439493, 2018). "The genotype of mIDH1 glioma in practice is heterozygous, and the likely presence of both mIDH1 and wtIDH1 subunits within a mutated heterodimer manifests as concurrently occurring forward and reverse IDH1 reactions respectively." (PMID 29303363, 2018). "IDH1/2 mutations occur frequently in low-grade glioma and secondary glioblastoma (~80%), but can also occur in acute myeloid leukemia (20%), angioimmunoblastic T-cell lymphomas (20%), and rarely in other malignancies such as thyroid, colorectal, and prostate cancer." (PMID 28748451, 2018). "IDH1 or IDH2 mutations represent early genetic event in the complex process of glioma development." (PMID 30279357, 2018). "Recent meta-analysis confirmed the prognostic role of IDH1/2 mutations in gliomas as well." (PMID 29662659, 2018). "IDH1 mutations have been found to less commonly occur in older people with glioblastoma, and the results of our mutational signature analyses provide molecular support for this finding in glioblastoma multiforme and brain lower grade glioma." (PMID 30412573, 2018). "To determine whether the same phenotype was observable in vivo, we first investigated the expression of PYCR1 and PYCR2 in low-grade gliomas, in which IDH1 mutations are commonly observed." (PMID 29562167, 2018).
glioma (continued). "Moreover, recurrent glioma cells can delete or amplify the IDH1 mutant or wild-type allele, which is followed by clonal expansion and recurrence of tumors that resembled the G-CIMP-low primary subtype." (PMID 29642018, 2018). "More recently, it has been shown that gliomas with a proneural gene expression signature displayed a distinct underlying (epi-)genetic phenotype consisting of a specific glioma-CpG island methylation phenotype (G-CIMP) related to IDH1 mutations." (PMID 29844871, 2018). "However, the mechanism underlying the improved prognosis in patients with glioma carrying IDH1 mutations is not fully understood." (PMID 30388142, 2018). "In this regard, (R)-2-hydroxyglutarate, the phenotypic expression of the genetic mutations in IDH1/2, may serve as a clinical biomarker for gliomas with such genetic mutations." (PMID 30192797, 2018). "In addition, recent work has suggested that downregulation of RAP1 and XRCC1 licenses IDH1-mutant glioma cells to engage the ALT mechanism after ATRX loss." (PMID 30226859, 2018). "The evaluation of BRAFV600E and IDH1/2 mutation status may be helpful in distinguishing PXAs from diffusely infiltrating gliomas, and useful for the therapeutic implications of PXAs." (PMID 30250216, 2018). "IDH1 down-regulation during the early stages of skin tumorigenesis is strongly correlated with tumor promotion; moreover, IDH1 mutations are frequently found in melanoma and various other cancers, including leukemia and glioma, and contribute to metastasis by altering cellular metabolism." (PMID 29165315, 2017). "In addition to glioma, IDH1/2 mutations (IDH1/2MUT) occur in substantial percentages in various other tumor types, such as acute myeloid leukemia (20–40%), chondrosarcoma (60%), intrahepatic cholangiocarcinoma (20%) and melanoma (5–10%)." (PMID 28467784, 2017). "However, further investigation needs be performed to reveal the relation between N-cadherin or other EMT markers/inducers and key parameters for new 2016 WHO glioma classification, such as IDH1 mutation, 1p/19q co-deletion or MGMT promoter methylation." (PMID 28851312, 2017). "Glioma patients, however, with IDH1 codon 132 mutation experienced a better prognosis." (PMID 28403884, 2017). "IDH1 mutations were present commonly in 70% of lower grade gliomas and secondary GBMs." (PMID 29371945, 2017). "Since IDH1 mutations are prominently found in the proneural subtype of glioma, these findings suggest that the BT142 model may be most similar to classical IDH1 mutant patients." (PMID 29062039, 2017). "IDH1 is frequently mutated in the majority of low grade gliomas and secondary high grade gliomas." (PMID 29046615, 2017). "In the specific targeting of the IDH1 R132H mutation through B-cell cloning, a novel rabbit monoclonal antibody was produced that promises to be a useful tool for overcoming the diagnostic challenge of differentiating between different subtypes of glioma." (PMID 31548536, 2017). "Consequently, new reliable methods for direct visualization of pathological microvascularity in gliomas must be developed for preoperative estimation of the tumour grade and IDH1 mutational status." (PMID 27300198, 2017). "Next, Prof. Yu Yao from Huashan Hospital of Fudan University reported the recent progress of his team in glioma immunology after stating the importance of genes encoding IDH1 and telomerase reverse transcriptase (TERT), as well as 1p/19q codeletion in classifying glioma." (PMID 28797870, 2017). "Another SNP, rs55705857-G, recently found to be associated with increased risk in IDH1/2-mutant gliomas, is positioned within a single chromatin topologic domain with MYC, and increases the activity of the MYC transcriptional network, as compared to the reference allele." (PMID 28587062, 2017). "The majority of low-grade gliomas and secondary glioblastomas harbor the IDH1 mutation." (PMID 29057925, 2017). "It has been proven experimentally through the detection of IDH1/2 mutations in gliomas." (PMID 28403884, 2017).
glioma (continued). "Moreover, studies in glioma cells with the R132H IDH1 mutation revealed that selective inhibition of GLUD2 expression markedly slows cell growth." (PMID 28208702, 2017). "Of note is that the G-CIMP phenotype is associated with IDH1 mutations in gliomas." (PMID 28122345, 2017). "However, the majority of driver pathways (196/209, 93.78%) unraveled by drgap in glioma patients with IDH1 mutations overlapped with those (196/214, 91.59%) in glioma patients without IDH1 mutations." (PMID 29046615, 2017). "Reportedly, among the three isoforms of IDH in humans, frequent somatic mutations of IDH1 have recently been found in certain cancers including nearly 80% in grade II-III gliomas, appropriate 45% in secondary glioblastoma multiforme (GBM), and 33%-50% in adult primitive neuroectodermal tumor." (PMID 28498812, 2017). "The high incidence of glioma-specific IDH1 mutations has implicated them as an early event that occurs during gliomagenesis and provides utility in distinguishing low grade astrocytomas and oligodendrogliomas, as well as secondary glioblastomas from reactive gliosis and primary glioblastomas." (PMID 31548536, 2017). "Similarly, the assay unambiguously identifies the IDH1-R132H mutation in glioma, with 50% mutant/wild type reads, confirming heterozygosity for this mutation." (PMID 28900252, 2017). "An R132H mutation in the isocitrate dehydrogenase (IDH1) gene prolongs the life of glioma patients." (PMID 28445981, 2017). "The results demonstrated that age (HR = 1.075, P < 0.001), WHO grade (HR = 9.560, P < 0.001), CCDC109B expression (HR = 1.861, P < 0.001), and mutation status of isocitrate dehydrogenase 1 (IDH1, HR = 0.244, P < 0.001), were all prognostic indicators for glioma patients." (PMID 28754121, 2017). "In summary, these findings suggested that novel specific inhibitors of mutant IDH1 may become a new therapy for glioma, AML and other cancers with IDH1 mutation." (PMID 28498812, 2017). "Finally, the IDH1 mutations prevalent in lower grade gliomas and recurrent glioblastomas appear to induce their oncogenic effects, at least partly, by heightening the oxidative stress and inflammatory responses." (PMID 28346397, 2017). "Furthermore, we demonstrate that IDH1 R132H mutation affects cellular redox status and sensitizes gliomas cells with IDH1 R132H mutation to 5FU treatment." (PMID 28052098, 2017). "Several authors suggested that the mutation of IDH1 could occur in early stages of the glioma formation and could lead to tumor progression towards GBM." (PMID 28948065, 2017). "IDH1 gene mutations have been widely studied in glioma or leukemia patients." (PMID 28403884, 2017). "Consistently, our findings reveal that IDH1-mutated gliomas display lower protein levels of Mcl-1." (PMID 29057925, 2017). "NADPH production is decreased by more than 40% in gliomas with the IDH1 mutation." (PMID 28939850, 2017). "Besides AML, IDH1 mutation is present in 77% of lower-grade glioma and 7% of glioblastoma in the 12 cancers we analysed." (PMID 28561042, 2017). "Notably, patients with gliomas harboring IDH1/2 mutations have an overall survival (OS) benefit over patients without an IDH1/2 mutation." (PMID 28698530, 2017). "For glioma with IDH1 R132H mutant, which caused the activation of AKT-mTOR signaling pathway, targeting AKT-mTOR could be adopted to abolish its effects on migration and invasion." (PMID 28052098, 2017). "70–90 % of grades II and III glioma and secondary GBMs carry mutated IDH1 or IDH2 genes." (PMID 27752843, 2017). "Additionally, Agios is pursuing a brain-penetrant dual mIDH1/2 inhibitor, AG-881, currently in phase I for advanced solid tumors including gliomas containing an IDH1/2 mutation (NCT02481154)." (PMID 28986582, 2017).
glioma (continued). "Furthermore, we confirmed the role of IDH1 R132H mutations in affecting cellular redox status using glioma cell lines, and provided evidence to further explore the application of chemotherapy such as 5-FU in the treatment of gliomas with IDH1 R132H mutation." (PMID 28052098, 2017). "Isocitrate dehydrogenase (IDH1) mutations are frequent in glioma patients." (PMID 28445981, 2017). "However, it is interesting that gliomas with mutated IDH1 have improved prognosis compared to gliomas with wild-type IDH." (PMID 28052098, 2017). "The IDH1 R132H mutation promotes the survival of glioma patients." (PMID 28445981, 2017). "IDH1 mutations are common in gliomas and have a positive impact on prognosis." (PMID 27655638, 2016). "Chromothripsis was recently described in gliomas with IDH1 gene mutation." (PMID 26865861, 2016). "More recently, a large cohort study described five glioma groups based on 1p/19q codeletion, IDH1/2 and TERT promoter mutational profile, with important clinical impact, with the “triple-negative” group or the only TERT-mutated group exhibiting a higher mortality risk." (PMID 27172220, 2016). "Studies on IDH1 mutations in glioma and acute myeloid leukemia (AML) have been well developed." (PMID 27863386, 2016). "In malignant glioma, IDH1 mutations are ubiquitous in tumor cells, and IDH1 mutations precede secondary and tertiary lesions, suggesting that IDH1 mutations are an early causative event in the genesis of gliomas." (PMID 27245697, 2016). "Similar reduction of glutathione levels was also observed in glioma bearing IDH1 or IDH2 mutation which accumulates 2-HG, suggesting that this oncometabolite may support ROS formation through attenuating the anti-oxidant system." (PMID 27358718, 2016). "Further work on the nature of circulating tumor material will be necessary to determine whether it will be possible to monitor the IDH1 mutation status in the peripheral blood of all patients with mutant gliomas." (PMID 26858939, 2016). "However, the evidence for low-grade gliomas and the prognostic value of IDH1 mutation is slightly more controversial." (PMID 26858939, 2016). "Initially, 5hmC loss in gliomas was proposed to be related with IDH1/IDH2 mutations." (PMID 26864347, 2016). "This newly revealed PTEN-independent mode of mTORC1/2 activation via the mutated IDH/2HG/KDM4A/DEPTOR pathway may provide an additional molecular mechanism to explain the oncogenic activity of IDH1/2 mutations in glioma and other cancers." (PMID 27624942, 2016). "Consistent with a relationship between IDH1 mutational status, ECM stiffness and glioma aggression, ectopic expression of the R132H IDH1 mutation significantly improved the survival of nude mice bearing xenografts derived from either primary GBM cells or the U87 cell line." (PMID 27820599, 2016). "Indeed, IDH1 mutations have been predominantly identified in secondary glioblastoma and low-grade gliomas, with mutations in more than 70% of cases." (PMID 26858939, 2016). "Mutations in isocitrate dehydrogenase 1 (IDH1) are characteristic of low-grade gliomas." (PMID 27144334, 2016). "IDH1/2 mutational status is the primary prognostic indicator for glial tumors." (PMID 27923049, 2016). "However, several studies have shown a higher rate of malignant transformation in IDH-mutated low grade glioma than in wild-type IDH1 tumors, showing that a subset of patients with the IDH1 mutation are characterized as having secondary glioblastoma." (PMID 27323413, 2016). "IDH2 mutations are also significantly less common in glioma than their IDH1 counterparts suggesting that IDH1 mutations may be more advantageous to the tumor cells than IDH2 mutations." (PMID 28480226, 2016). "Enchondromatosis patients with an IDH1 R132H mutation could have a higher risk of developing gliomas than patients with an IDH1 R132C mutation." (PMID 27036230, 2016).